BCHE (butyrylcholinesterase)
Diseases named in the same sentence as BCHE in open-access papers (continued):
Sharing a sentence is not in itself a finding about the gene and the disease.
dementia (36 papers, 2010 to 2026). Loss of intellectual abilities interfering with an individual's social and occupational functions. "Increased post-stroke BChE has been previously reported to be associated with delirium, mortality prediction, and dementia." (PMID 40520612, 2025). "Decreased BChE activity has been associated with increased inflammation, increased risk of postoperative delirium, and dementia." (PMID 36474266, 2022). "Anticoagulant therapy with DOACs may reduce cardiovascular risk factors in the development of the AD-related dementias, whereas inhibitors of AChE and/or BChE may restore the cholinergic transmission in the AD brain at different disease stages." (PMID 35807514, 2022). "Independent risk factors were performed for BChE activity, PD, and related dementia." (PMID 28840123, 2017). "Butyrylcholinesterase (BChE), as the sister enzyme of AChE, also has a similar effect on butyrylcholine in dementia." (PMID 41304636, 2025). "A validated docking setup was employed to examine the ligand-receptor interactions and binding mechanisms of bambuterol (binding score = -− 7.99 kcal/mol) with the dementia-related enzyme butyrylcholinesterase, identifying it as a potential inhibitor." (PMID 40542029, 2025). "The ability of lipid-lowering drugs such as statins to inhibit BChE suggests a potential role in dementia prevention." (PMID 40116876, 2025). "Inhibitors of acetylcholinesterase (AChE) and butyrylcholinesterase (BChE) are normally the drugs of choice to cure dementia and related diseases." (PMID 38420420, 2024). "While eseramine has a less inhibitory effect against acetylcholinesterase than physostigmine, physovenine was patented as an inhibitor of acetylcholinesterase and butyrylcholinesterase as well as for the treatment of AD and dementia." (PMID 36501282, 2022). "Acetyl- (AChE) and butyrylcholinesterase (BChE) inhibitors are used, e.g., to treat dementias and myasthenia gravis." (PMID 35455397, 2022). "Physovenine was patented as an inhibitor of acetylcholinesterase and butyrylcholinesterase as well as for the treatment of AD and dementia (EP0949920, WO9902154)." (PMID 31937840, 2020). "Two enzymes hydrolyzing the neurotransmitter acetylcholine — AChE and BChE, play important roles in the clinical course and pathogenesis of AD and AD-type dementia." (PMID 30890752, 2019). "This study aim to determine changes of serum butyrylcholinesterase (BChE) activity in PD patients and related dementia." (PMID 28840123, 2017). "Logistic regression analysis then confirmed that both BChE activity and advanced stage were independent correlation factors for PD-related dementia." (PMID 28840123, 2017). "Mini-Mental State Examination is the most popular scale to determine possible dementia and a positive correlation was also found between serum BChE activity and MMSE score." (PMID 28840123, 2017). "Rivastigmine that inhibits both AChE and BChE was found to be a more effective anti-impulsivity agent in dementias." (PMID 28243210, 2017). "The present study aimed to determine changes of serum BChE activity in PD patients and related dementia." (PMID 28840123, 2017). "In conclusion, BChE activity can be regarded as a biomarker in PD, especially in PD-related dementia." (PMID 28840123, 2017). "Receiver operating characteristic (ROC) curves were obtained to explore serum BChE activity in distinguishing PD patients and related dementia." (PMID 28840123, 2017). "Gender, albumin, BMI, and dementia were all independent correlation factors for serum BChE activity." (PMID 28840123, 2017). "In PD patients, we found that dementia as well as gender, albumin, and BMI, was an independent correlation factor for BChE activity." (PMID 28840123, 2017). "All γ-carboline-phenothiazine conjugates have been assessed as inhibitors of AChE and BChE, which are important for AD and/or AD-like dementia development and structurally close enzyme—CaE." (PMID 26281952, 2015).
dementia (continued). "Parkinson Disease Dementia (PDD) - BChE is involved in Parkinson disease dementia (PDD)." (PMID 40612057, 2025). "In all of thesecases, duloxetine in addition to its primary antidepressive effectmay offer beneficial clinical outcomes, such as improved cognitionand prevention against dementia by augmenting the cholinergic functionthrough its secondary mode of action as a BChE inhibitor." (PMID 39246500, 2024). "Neurodegeneration might also be prevented by inhibiting enzymes such as acetylcholinesterase, butyrylcholinesterase, and tyrosinase among patients with dementia." (PMID 36297533, 2022). "The ROC curve was analyzed for serum BChE activity to detect patients with dementia." (PMID 28840123, 2017). "Serum BChE activity can be regarded as a biomarker for PD and related dementia." (PMID 28840123, 2017). "In future, it may be necessary to explore the development of potential new anti-BChE drugs for treating AD and related dementias." (PMID 20550720, 2010). "As a drug target, it has been observed that BChE inhibition may also be more effective for the treatment of AD and related dementias." (PMID 20550720, 2010). "Furthermore, BChE-associated pathology is not present in any other dementias, such as frontotemporal dementia with tau or dementia with Lewy bodies." (PMID 38061987, 2023). "Moreover, the inclusion of cymserine, a highly potent selective BChE inhibitor in the clinical trials for AD treatment, proved that BChE inhibition could be an essential tool for the treatment of AD and related dementias." (PMID 36969847, 2023). "Moreover, the inhibition of acetylcholinesterase (AChE) and butyrylcholinesterase (BChE), enzymes responsible for the hydrolysis of ACh following synaptic release, has thus been suggested as a promising strategy to avoid the progression of dementia." (PMID 36431805, 2022). "Decreased BChE activity has been associated with increased risk of postoperative delirium in several studies —though this finding is not universal —and has been associated with dementia." (PMID 36474266, 2022). "BChE activity could serve as a biomarker for detecting PD and related dementia in clinic." (PMID 28840123, 2017). "However, BChE activity could serve as a biomarker in PD patient to assess disease severity, discriminate PD-related dementia, evaluate efficacy of drugs, and instruct physicians about the course of clinical medications for dementia." (PMID 28840123, 2017). "Hence, AD and other form of dementia could be treated by the use of agents that restore the level of acetylcholine through the inhibition of both major form of cholinesterase enzymes AChE and BChE." (PMID 29169349, 2017). "Although its function has not been definitively clarified, BChE is a predictor for two-year major cardiac events, as well as for Parkinson’s disease and related dementia." (PMID 31653081, 2019). "BChE activity decreased in PD-related dementia compared with those without dementia." (PMID 28840123, 2017). "Thus, their nutritional state was poorer, and BChE activity was lower than patients without dementia." (PMID 28840123, 2017). "Patients with dementia had lower BChE activity than patients without dementia." (PMID 28840123, 2017).
Cognitive impairment (28 papers, 2016 to 2025). Abnormal cognition is characterized by deficits in thinking, reasoning, or remembering. "Therefore, the ability of these plant-derived compounds to inhibit both AChE and BChE indicates a promising therapeutic strategy for restoring cholinergic function and alleviating cognitive impairments associated with AD." (PMID 40002547, 2025). "Also, plasma butyrylcholinesterase activity (whose increased activity is associated with cognitive impairment) was evaluated as a possible biomarker for differential diagnosis between AD and LBD, finding a lower activity in the last." (PMID 40256832, 2025). "We found lower MMSE1 scores among the patients carrying the CC genotype of BCHE rs1803274 than among those carrying the CT genotype (p = 0.012), suggesting worse cognitive impairment." (PMID 40423221, 2025). "Chrysin was found to lower the cognitive impairment induced by aluminum chloride and normalize acetylcholinesterase and butyrylcholinesterase activity in the hippocampus." (PMID 40059876, 2025). "Considering the role of AChE and BChE in suppressing neurotransmitter acetylcholine levels, numerous studies have demonstrated its potential as a therapeutic target for alleviating cognitive impairments in AD and SZ." (PMID 40002349, 2025). "For example, in a retrospective analysis patients with mild cognitive impairment, rivastigmine, which inhibits both AChE and butyrylcholinesterase (BChE, EC 3.1.1.8), reduces whole brain atrophy, hippocampal atrophy, and white matter loss." (PMID 32414155, 2020). "There are some naturally occuring AChE/ butyrylcholinesterase (BChE) inhibitors as well-known as physostigmine and huperzine A from plant origin that show effective cognitive impairment." (PMID 30123124, 2018). "Altogether, these data suggest that BChE is a potential therapeutic target for restoring ACh levels in the brain and thus improving cognitive impairment, while also minimizing adverse effects in patients with progressive AD." (PMID 28000737, 2016). "Similarly, administration of extracts from Vernonia amygdalina, Amygdalus spinosissima, and Bergenia ciliata demonstrated protective effects against SCO-induced cognitive impairment by significantly reducing both AChE and BChE activity in treated animals." (PMID 40002547, 2025). "Our research on MsA in N2a/APP695swe cells and scopolamine-induced cognitive impairment mouse models demonstrates that MsA significantly elevates ACh levels while effectively inhibiting AChE and BChE enzymes, highlighting its regulatory function in the cholinergic system." (PMID 41007261, 2025). "In the AD hypothesis, these neurotransmitters decrease as a result of overexpression of AChE and BChE, leading to cognitive impairment." (PMID 32887386, 2020). "A low level of the cholinergic neurotransmitter, acetylcholine, correlates with cognitive impairments in AD cases; hence, inhibition of the acetylcholinesterase (AChE) and butyrylcholinesterase (BChE), the acetylcholine degrading enzymes, might delay AD onset." (PMID 32824050, 2020). "In-vivo active selective reversible BChE inhibitors are thus highly desirable not only as potential clinical candidates for improving memory and cognitive deficits in patients with progressive AD, but also as molecular tools for studying the potential of BChE as a therapeutic target." (PMID 28000737, 2016). "Hence, inhibition of AChE and BChE activities and stimulation of Na+/K+-ATPase activity by tested extracts can provide an avenue for the development of effective drugs of plant origin for the management of cognitive disorders." (PMID 37006627, 2023). "However, due to the limitations of AChE inhibitors, including dosage constraints and inadequate long-term efficacy, BChE inhibitors are emerging as a new therapeutic target, suggesting that inhibiting BChE could be a potential therapeutic approach for cognitive impairments in SZ, BPD, and MDD." (PMID 40002349, 2025).
Cognitive impairment (continued). "Notably, two genes, BCHE and CCS, along with biomarkers such as carotene, vitamin E, and bilirubin, demonstrate a significant relationship between psychiatric disorders and cognitive impairment." (PMID 40002349, 2025). "Behavioral assessments (Novel Object Recognition, Morris Water Maze) quantified cognitive impairment in scopolamine-treated mice, complemented by histological (Nissl staining, BDNF IHC), biochemical (ACh, AChE, BChE), and molecular (BDNF, CREB) analyses of hippocampal and cortical tissues." (PMID 41007261, 2025). "However, where the new BChEi with selective reversible nanomolar BChE inhibition was given to dogs with moderate cognitive impairment, no side effects were observed throughout the study." (PMID 34518582, 2021).
Parkinson disease (26 papers, 2010 to 2025). A progressive degenerative disorder of the central nervous system characterized by loss of dopamine producing neurons in the substantia nigra and the presence of Lewy bodies in the substantia nigra and locus coeruleus. "Our study assessed seed oils’ in vitro neuroprotective potential from borage, calophyllum, and prickly pear, specifically targeting AChE, BChE, and tyrosinase, enzymes associated with Alzheimer’s and Parkinson’s disease." (PMID 40563295, 2025). "In Parkinson’s disease, BChE contributes to the imbalance between the cholinergic and dopaminergic systems." (PMID 40563465, 2025). "Both AChE and BChE are crucial in the treatment of neurodegenerative disorders such as Myasthenia gravis, Alzheimer and Parkinson’s disease, since generally all drugs in use act by inhibiting AChE and BChE activity." (PMID 28573890, 2017). "For example, Parkinson’s disease (PD), which involves both dopaminergic and cholinergic dysfunction, may benefit from the modulation of BChE activity." (PMID 40563465, 2025). "Nevertheless, other enzymes may be potential targets for pesticides, such as other cholinesterases, e.g., butyrylcholinesterase (BChE), or tyrosinase, the latter is involved in dopamine metabolism and potentially involved in Parkinson’s disease." (PMID 36006126, 2022). "Both AChE and BChE are crucial in the treatment of neurodegenerative disorders such as myasthenia gravis, Alzheimer and Parkinson’s disease, since so far the most successful approach in treating these disorders has been the use of cholinesterase inhibitors that target primary AChE." (PMID 30289893, 2018). "Similarly, carbamates like donepezil have been shown to exert some degree of selective BChE inhibition under specific conditions, making them viable candidates for future exploration in diseases with pronounced BChE activity, such as AD and Parkinson’s disease." (PMID 40563465, 2025). "As far as we know, N-[2-(substituted-phenyl)ethyl]-4-quinazolinamines have been reported as acetyl- and butyrylcholinesterase inhibitors (AChE IC50 = 6.2 μM; BuChE IC50 = 14.1 μM) for the treatment of Parkinson disease and inhibitors of NFκB." (PMID 33435251, 2021). "Indeed, AChE and BChE inhibition may slow neurodegeneration in AD and Parkinson's disease (PD)." (PMID 29344419, 2017). "Serum BChE activity in Parkinson's disease has not yet been clearly determined, and we report it for the first time." (PMID 28840123, 2017). "Although AChE activity reportedly decreases in Parkinson's disease, the relationship between BChE activity and Parkinson's disease had not been clearly performed." (PMID 28840123, 2017). "However, the declined BChE activity was inconsistent with a former study, which indicated that BChE activity was not significantly altered in Israeli Parkinson's disease patients compared with younger healthy controls." (PMID 28840123, 2017). "Then a subgroup analysis found no alterations between patients with and without smoking history, suggesting that only BChE activity correlated with Parkinson's disease independent of hepatic function, smoking history, metabolic syndrome, or any other clinical characteristics." (PMID 28840123, 2017).
Sepsis (26 papers, 2015 to 2025). Sepsis is defined as life-threatening organ dysfunction caused by a dysregulated host response to infection. "Recent evidence suggests that preoperative BChE levels inversely associate with postoperative ileus and sepsis risk, potentially reflecting impaired cholinergic anti-inflammatory pathways." (PMID 40129922, 2025). "In colorectal surgery, low preoperative levels of butyrylcholinesterase (BuChE) have been associated with an increased risk of surgical site infections and sepsis." (PMID 40428771, 2025). "Lower BChE activity in pediatric patients with sepsis is associated with increased mortality in the PICU setting." (PMID 40861055, 2025). "In patients diagnosed with sepsis-3, lower BChE levels was identified as an independent risk factor for 30-day mortality." (PMID 40612057, 2025). "The present study highlights the validity and prognostic power of BChE measurements for early detection of high-risk, life-threatening sepsis." (PMID 29853783, 2018). "The sustained decrease in BChE activity observed in deceased patients suggests that serum cholinesterase is a new risk warning indicator in the intensive care setting, an indicator that allows simple and rapid screening of patients at risk for sepsis." (PMID 36505241, 2022). "Recent studies have shown that acetylcholinesterase (AChE) and butyrylcholinesterase (BChE) may serve as important diagnostic and therapeutic targets in sepsis." (PMID 30804708, 2019). "Collectively, these studies highlight that patients with sepsis typically exhibit persistently low BChE activity, underscoring its prognostic relevance in critically ill populations." (PMID 40861055, 2025). "Research shows that lower plasma BChE levels correlates with higher mortality rates in sepsis patients." (PMID 40612057, 2025). "Decreased perioperative BChE levels have been correlated with higher SSI incidence, increased sepsis risk, prolonged intensive care stays, and higher postoperative morbidity." (PMID 41157220, 2025). "Several studies report that BChE activity is markedly reduced when adults or children are admitted with sepsis or septic shock, a decline attributed to both impaired hepatic synthesis and enzyme consumption during systemic inflammation." (PMID 40861055, 2025). "BChE was directly correlated with leukocyte count and inversely correlated with bilirubin and sepsis (p-value < 0.01)." (PMID 39229253, 2024). "In a study of 453 patients, BChE was negatively correlated with complications, sepsis, and changes in nutritional status." (PMID 39229253, 2024). "A rapid decrease in BChE activity was described as a physiological response to sterile inflammation after surgery and trauma, while a delayed decrease in BChE activity was described in response to sepsis." (PMID 37629287, 2023). "POCT-measured BChE activity can facilitate the early detection of systemic inflammation and correlates with disease severity and patient outcome in sepsis, trauma, and burns." (PMID 36140551, 2022). "We have demonstrated that BChE activity is a predictor for 28- and 90-day mortality in patients with burns or sepsis." (PMID 36140551, 2022). "A rat study of sepsis suggested that BCHE can function as an inflammatory marker in sepsis, further supporting its role in inflammation." (PMID 35967794, 2022). "A BChE activity cut-off value of 1.661 kU/L at the clinical onset of sepsis with an ICU admission and BChE cut-off value of 2.644 kU/L in the emergency room following a severe burn trauma were predictive for a potentially fatal outcome." (PMID 36140551, 2022). "BChE activity in this cohort of critically ill COVID-19 patients were consistently lower than the previously reported cut-off values in sepsis and burns." (PMID 36140551, 2022). "Point of care testing (POCT) of butyrylcholinesterase (BChE) enables early detection of systemic inflammatory responses and correlates with disease severity in sepsis and burns." (PMID 36140551, 2022).